SELP (selectin P)
Diseases named in the same sentence as SELP in open-access papers (continued):
Sharing a sentence is not in itself a finding about the gene and the disease.
tumor (continued). "This underscores 1,8-cineole’s potential as a targeted disruptor of the P-selectin-PSGL-1 axis, offering a novel approach to mitigate platelet-driven tumor-promoting interactions." (PMID 40538536, 2025). "SELP and ALOX5 are highly expressed in some tumours and cancer cell lines, inducing cancer cell proliferation and inhibiting apoptosis." (PMID 37816387, 2023). "Localization of FiVis nanoparticles to tumours was abrogated in P-selectin knockout (KO) SHH-MB mice (SELP null SHH-MB, Ptf1acre/+; Ptch1fl/fl; Selp−/−), further confirming the importance of P-selectin for BBB penetration." (PMID 36864161, 2023). "The connection between SELP and CD34 shows that patients gain from the stimulation of the innate immune response to improve anti-tumor immunity, eliminate tumor cells, and hinder the growth of tumors." (PMID 37818360, 2023). "SELP+ HEVs and APOD+ myCAFs foster favorable immunomodulatory stromal niches for improved outcomes, while STMN1+ cECs and MYF5+ MSCs form immunosuppressive niches in tumor invasion regions, highlighting therapeutic targets." (PMID 40107247, 2025). "The sub‐clustering of ECs revealed six subtypes, including extra‐alveolar capillary EC (cEC) (FCN3+EDN1+PLVAP+), alveolar cEC (HPGD+EDNRB+IL1RL1+), arterial EC(GJA5+FBLN5+DKK2), lymphatic EC (CCL21+TFF3+FABP4), INSR+ tumour EC (INSRhiHSPG2+PLVAP+), and ACKR1+ tumour EC (ACKR1+SELP+IL1R1+)." (PMID 35184398, 2022). "Although increased T cell infiltration and activation, and caspase staining were also observed, our results with human GB xenografts in immunodeficient mice indicated that the effect of SELP inhibition on tumor growth is not T cell-dependent." (PMID 33771989, 2021). "Furthermore, the results with human U251, patient-derived xenografts (PDX) and GL261 mouse models revealed positive staining of SELP and PSGL-1 in tumor areas enriched with activated microglia." (PMID 33771989, 2021). "It was previously shown that cell surface molecule CD24 expressed on tumor cells can support rolling on P-selectin and thus CD24-P-selectin pathway may be an important element in recruiting tumor cells to target organs." (PMID 21714887, 2011). "The presence of the P‐selectin protein on the platelet membrane surface, with a strong affinity for the CD44 receptor highly expressed by tumor cells, facilitated the endocytosis process of PSAB and resulted in an improved capacity for prolonged blood circulation and enhanced tumor targeting." (PMID 39033534, 2024). "To further characterize the influence of SELP-PSGL-1 interactions on GB cells and the brain microenvironment, we performed single-cell RNA-seq of shNC and shSELP GL261 tumors focusing on three main subpopulations: tumor cells, T cells and microglia/macrophages." (PMID 33771989, 2021). "After neoadjuvant treatment, responders exhibited higher SELP and VWF expression in tumor than non-responders, and the main components of TU-HEV endothelial cells may attribute to high immune infiltration." (PMID 37537219, 2023). "The tumor platelets could perhaps behave in a 'semi-activational state'23 but absence of activation, and overexpressed the ITGA2B and SELP mRNA but not protein in the initial of tumorgenesis." (PMID 31523198, 2019).
cancer (244 papers, 2007 to 2025). A tumor composed of atypical neoplastic, often pleomorphic cells that invade other tissues. "Selenoproteins that are directly or indirectly involved in maintaining redox homeostasis, including GPX, TXNRD1, SelF, and SelP, seem to influence a myriad of signaling pathways that are implicated in the initiation and advancement of cancer." (PMID 39839762, 2024). "The platelet activation markers CD40L and P-selectin play immunosuppressive effect and are used as indicators of disease progression in cancer or cancer-associated venous thromboembolism (VTE) patients." (PMID 37170255, 2023). "After platelet activation, P-selectin present on the platelets surface is bound to CD24 ligand found on the surface of cancer cells, causing their adherence to endothelial cells." (PMID 23554823, 2013). "Overall, extensive research has conclusively shown that levels of SelP are consistently diminished across a multitude of cancer types." (PMID 39839762, 2024). "P-selectin binding to integrins and resulting P-selectin signaling and cell–cell interactions are expected to play a role in inflammation and cancer metastasis in addition to P-selectin–PSGL-1 interaction." (PMID 37759488, 2023). "One of the key factors in cancer growth and metastasis is the P-selectin protein which has a significant role in the activation of platelets associated with cancer cell metastasis." (PMID 37571136, 2023). "Fucoidan exhibits binding affinity to P-selectin and the targeting effect on P-selectin-positive cancer cells." (PMID 33467201, 2021). "These single cell RNA-seq results demonstrated that SELP knockdown in the cancer cells resulted in alteration of the microglia/macrophage." (PMID 33771989, 2021). "It was suggested that P-selectin plays a decisive role in the interactions of cancer cells with platelets, thus facilitating adhesion to the endothelium and promoting metastasis." (PMID 32575485, 2020). "However, the actual associations between SelP concentrations and cancer incidence are unknown." (PMID 25599275, 2015). "Some of these cancer-related genes were associated with processes occurring in the extracellular matrix and related to DCN: CXCR4/CXCL12 axis, SELP, vWF, COL3A1, SCARA, SPARCL1." (PMID 26437222, 2015). "P-selectin participates in both the pathogenesis of thrombosis, as well as in the inflammatory processes in cancer patients." (PMID 23554823, 2013). "Taken together, this study’s findings suggest that ED and SELP’s roles are not merely associated with the presence of VTE but are closely linked with their impact in the context of ongoing cancer." (PMID 39768338, 2024). "During the inflammatory response, specifically the acute phase reaction, SelP biosynthesis is reduced, which disrupts selenium transport and selenium metabolism, which may result in lower selenium levels in cancer patients." (PMID 39839762, 2024). "SELP expression presents small differences in the early stages that increase in the advanced, indicating that the difference in the expression of this gene gradually grows with the progression of cancer." (PMID 36447000, 2023). "Coxsackievirus B 1 and 3 interact with human platelets to trigger SELP expression, and SELP has predictive value in various cancers; however, the relationship between SELP and RNA modification in GC carcinogenesis and development remains unclear." (PMID 37061682, 2023). "Moreover, comparing normal samples with cancer samples, SELP was downregulated in most types of cancer." (PMID 37408763, 2023). "Therefore, targeting and inhibiting the action of P-selectin protein is an essential mechanism for achieving effective cancer therapy." (PMID 37571136, 2023). "P-selectin plays a central role in mediating the interactions between cancer cells and platelets." (PMID 37046814, 2023).
cancer (continued). "These direct and indirect changes in the cancer cell populations may be induced by blocking the binding of the membrane-bound SELP expressed on the cancer cells to PSGL-1 expressed on the microglia/macrophages." (PMID 33771989, 2021). "SELP is a member of the selectin family of cell adhesion molecules, and it mediates heterotypic aggregation of activated platelets to cancer cells and adhesion of cancer cells to stimulated endothelial cells." (PMID 34956309, 2021). "As our mechanistic data suggests, GPx4 significantly contributes to HCC protection by selenium, even if other selenoproteins as SELP, DIO1 and TXNRD2 show similar positive association with cancer survival and may also be involved." (PMID 29515790, 2018). "Notably, significant post-treatment upregulation of SELP+ high endothelial venules (HEVs) and APOD+ myofibroblastic cancer-associated fibroblasts (myCAFs), alongside a decline in STMN1+ capillary endothelial cells (cECs), is specific to the immunochemotherapy cohort." (PMID 40107247, 2025). "Research has demonstrated that selenoproteins, such as selenoprotein P (SelP), glutathione peroxidase (GPx), thioredoxin reductase (TXNRD), and selenoprotein F (SEP15, SelF), exert regulatory effects on tumorigenesis and tumor progression through modulation of cancer-associated signaling pathways." (PMID 39839762, 2024). "The aim of this study was to reveal whether the performed chemical selenylation of LP might cause a change in its anti-cancer activities such as growth inhibition and apoptosis induction, especially whether the selenylation extent could govern the anti-cancer activity of SeLP to the cells." (PMID 35565676, 2022). "Among the genes which were weakly expressed (33 ≤ Ct < 35) in ASC-based self-assembled scaffold, selectin P mediates interaction of endothelial or platelets with leukocytes and its biological importance is on the pathogeneses of inflammation, thrombosis and the growth and metastasis of cancers." (PMID 33805910, 2021). "Unlike classical anti-platelet drugs that primarily target platelet aggregation, 1,8-cineole specifically disrupts the P-selectin-PSGL-1 axis, addressing the inflammatory and immune-modulating aspects of cancer progression." (PMID 40538536, 2025). "Moreover, an influence of selenoprotein polymorphisms on the risk of breast (Gpx1, SelF, SelP) or colorectal (Gpx4, TrxR1, and TrxR2, SelP, SelF, and SelS) cancer was also found, which could indicate their important role in the etiology of these types of cancer." (PMID 34068374, 2021). "Overall, it is demonstrated that two selenoproteins, SELENOF (SelF) and SELENOP (SelP), are only positively correlated with ZIP8 across multiple cancer types (23/40 and 19/40, respectively)." (PMID 34768831, 2021). "Taken together, these findings are consistent with the hypothesis that SELP and CST2 may act as cancer progression-promoting genes in various tumors." (PMID 37061682, 2023). "Studying the correlation between the SELP-PSGL-1 axis and cancer-promoting transcription factors may reveal important pathways in GB progression that could be affected by the contribution of microglia to this axis." (PMID 33771989, 2021). "Our analyses of the gene expression data in (bulk) cancer tissues show that there is no or little correlation between CMAS and any siglec gene (SIGLEC1-16), selectin gene (SELE, SELL, and SELP) or their total expressions (data not shown)." (PMID 32296639, 2020).
infection (64 papers, 2005 to 2025). The state of being infected such as from the introduction of a foreign agent such as serum, vaccine, antigenic substance or organism. "In this small cohort, we only detected positive correlations between platelet-TLR9 and SELP, which was lost with infection." (PMID 40825056, 2025). "For example, P-selectin-positive platelets support the recruitment of circulating immune cells during infection." (PMID 36142161, 2022). "Gene SELP codes for selectin P, a protein that mediates and promotes leukocyte adhesion to endothelium, being essential for leukocyte recruitment to an infection site." (PMID 32928114, 2020). "The in vivo study further demonstrated an interaction of dietary Se and infection on SelP expression in different tissues, in an isoform specific manner." (PMID 30571741, 2018). "It is very interesting that changes in SelP expression are apparent 48h post infection, when the immune response is still in the innate stage but already initialising an adaptive response." (PMID 30571741, 2018). "Both, SELL and SELP were also up-regulated in bovine mammary tissue following experimental infection with either S. uberis or E. coli." (PMID 28419109, 2017). "The following research was conducted to elucidate the evolution and expression of salmonid selenoprotein P (SelP), a selenoprotein that is unique in having multiple selenocysteine (Sec) residues, following supranutritional selenium supplementation and infection in rainbow trout." (PMID 30571741, 2018). "Downregulation of SelP in infection/acute phase reaction may represent a mechanism to generate Se for incorporation into other selenoproteins that are more directly involved in immunity e.g. GPx1, TrxR1 and Selenoprotein K." (PMID 30571741, 2018). "In addition, Coussens and co-workers have established two genes (TNFSF8 and SELP) in a gene infection signature for Johne's disease in cattle." (PMID 17974019, 2007). "The expression of E-selectin (SELE), P-selectin (SELP), and integrin β2 (ITGβ2) also increased gradually in the Yb2- and cYb2ΔsspA-infected ducks as the infection time increased." (PMID 38594770, 2024).
cardiovascular disease (42 papers, 2009 to 2025). "Lastly, P-selectin plays a key role in the pathogenesis of cardiovascular diseases through their involvement in leukocyte adhesion and inflammation." (PMID 40094867, 2025). "Literature review revealed that SELP and PECAM1 are associated with angiogenesis and cardiovascular diseases, while CXCR4, IL2RG, and CD48 are primarily involved in immune responses." (PMID 40612110, 2025). "Among these, SELP and PECAM1 were mainly expressed in endothelial cells and are involved in angiogenesis and cardiovascular disease." (PMID 40612110, 2025).
cardiac disease (4 papers, 2020 to 2025). "Nonetheless, the results concerning the association between P-selectin plasma levels and heart diseases are still contradictory." (PMID 32053880, 2020).
metabolic disease (4 papers, 2023 to 2025). A congenital disorder (due to inherited enzyme abnormality) or acquired (due to failure of a metabolically important organ) disorder resulting from an abnormal metabolic process. "The SELP rs6136 G allele was more frequently associated with a CVD and/or metabolic disease history (GG/GT vs. TT; χ2, p = 0.018)." (PMID 39768338, 2024).
SELP also shares sentences with these, for which no sentence is quoted: ischemic stroke (36 papers); hypercoagulability (18); ischemia (18); dengue (12); metabolic syndrome (11); thrombotic disease (11); viral infection (11); atrial fibrillation (10); colitis (10); inflammation (10); peripheral artery disease (10); Cerebral ischemia (9); depression (9); myeloma (9); stable angina (9); acute myocardial infarction (8); coagulopathy (8); Hypercholesterolemia (8); thalassemia (8); inflammatory bowel disease (7); Nephropathy (7); transient ischemic attack (7); type 1 diabetes (7); vasculopathy (7); acute respiratory distress syndrome (6); cerebral infarction (6); cerebral malaria (6); diabetic nephropathy (6); hematologic malignancies (6); pneumonia (6).
A further 268 diseases each share a sentence with SELP in 6 papers or fewer.